IL6 (interleukin 6)
Diseases named in the same sentence as IL6 in open-access papers (continued):
Sharing a sentence is not in itself a finding about the gene and the disease.
liver cirrhosis (80 papers, 2007 to 2025). "Serum IL-6 levels have been shown to be closely related to HBV-associated liver cirrhosis and the risk of HBV-associated HCC." (PMID 35889747, 2022). "In this regard, increasing levels of IL-6 have been associated with higher mortality or the development of complications such as OHE in liver cirrhosis 23,24." (PMID 34654829, 2021). "While low baseline albumin and high bilirubin values were associated with high IL6, liver cirrhosis, alcoholic liver disease, and portal vein infiltration were associated with high IL8." (PMID 34080071, 2021). "Ascitic interleukin 6 is an easily-applicable proinflammatory biomarker with high prognostic and diagnostic relevance in critically ill patients with liver cirrhosis." (PMID 32899730, 2020). "The aim of the present study was to evaluate the prognostic and diagnostic potential of ascitic IL-6 in a challenging population of critically ill patients with decompensated liver cirrhosis." (PMID 32899730, 2020). "The increased serum levels of inflammatory markers (such as C-reactive protein, white blood cell count and IL-6) found in patients with liver cirrhosis have been implicated in the breakdown of the blood–brain barrier." (PMID 23406548, 2013). "As an inflammatory mediator, IL-6 may contribute to the progression of HBV-associated liver cirrhosis." (PMID 39071840, 2024). "Being a mediator of inflammation, IL-6 may be implicated in the progression of HBV-associated liver cirrhosis." (PMID 35119591, 2023). "Broader searches may be able to identify more studies on the association between IL-6 gene polymorphisms and liver cirrhosis." (PMID 37101651, 2023). "When classified as a dichotomic variable, according to the median values, the IL-6 levels over the median were significantly associated with liver cirrhosis (with χ2 = 9.77 and p = 0.002), and the IL-6 values were inversely related to the prothrombin activity (with ρ = −0.30 and p < 0.001)." (PMID 36009045, 2022). "The imbalance of Treg/Th17 maybe was caused by increased IL-6 level in patients with hepatitis B-associated liver cirrhosis." (PMID 31639000, 2019). "An increase of one unit (1 pg/mL) of the IL-1α concentration resulted in 8% increased risk of the liver cirrhosis, an increase of one unit (1 pg/mL) of IL-6 concentration implicated about 5% increased risk, and an increase of one unit (1 pg/mL) of HGF implicated 3% increased risk of liver cirrhosis." (PMID 26448742, 2015). "Although our study cannot provide proof of causal relationships, the strong association between serum IL-6 levels and decompensation during follow-up might be considered as a hint of a pathophysiological role of inflammation in decompensation of liver cirrhosis." (PMID 32357568, 2020). "Interestingly, IL-6 secreted by macrophages as the cause for a reduced intestinal barrier function was also discussed as a mechanism for the epithelial barrier defect found in liver cirrhosis." (PMID 31717494, 2019). "It has also been shown that the concentration of circulating IL-6 correlates positively with the stage of liver cirrhosis." (PMID 41020850, 2025). "Another study reported that IL-1α and IL-6 serum levels were significantly increased in alcoholic cirrhosis patients, being correlated with the progression of liver cirrhosis." (PMID 38473721, 2024). "Herein, our results indicated that the increase of Fendrr in liver cirrhosis patients is positively correlated with IL-6 production." (PMID 38762176, 2024). "Exclusion of liver cirrhosis patients showed that serum IL-6 of moderate cases was 18.2 (4.0–265) pg/mL and of severe cases was 35.2 (3.0–1175) pg/mL, and was higher in the latter cohort (p = 0.049)." (PMID 38791005, 2024). "In patients with liver cirrhosis, there were observed high levels of systemic IL-6 with a dysregulated acute phase response of the immune system." (PMID 38473721, 2024).
liver cirrhosis (continued). "Ethanol per se and liver cirrhosis, as a pro-inflammatory condition, promote the production of IL-6 and TNF-α, increasing the synthesis of RANKL and, consequently, promoting bone resorption." (PMID 38472981, 2024). "Patients with liver cirrhosis are characterized by increased serum IL-6 levels due to a higher synthesis of IL-6 in immune cells as well as an impaired hepatic removal of this cytokine." (PMID 37189804, 2023). "Fecal as well as plasma IL-6 levels were higher in patients with acutely decompensated liver cirrhosis but were similar between healthy controls and patients with stable liver cirrhosis." (PMID 37189804, 2023). "Patients with HBV-related liver cirrhosis exhibited more elevated IL-6 levels than those with active chronic HBV." (PMID 35119591, 2023). "IL-6, a primary immunomodulatory cytokine, has been shown related to liver cirrhosis in a few studies." (PMID 37101651, 2023). "Induction of CD14 + Trem-1 + iNOS + intestinal macrophages in liver cirrhosis patients released IL-6, NO, and accelerated intestinal permeability." (PMID 37273916, 2023). "Decompensated liver cirrhosis is often complicated by ascites, and circulating IL-6 levels are further increased in these patients." (PMID 37189804, 2023). "In the liver cirrhosis sample, two patients develop cytokine storm (progression of infectious inflammation, IL-6 increase: 480 pg/ml in the first patient and 280 pg/ml in the second patient)." (PMID 36394820, 2022). "Patients with manifest liver cirrhosis (F4) had significantly higher levels of M30, M65, IL-6 and IL-8." (PMID 34305638, 2021). "ROC analysis showed that IGF2 had the highest area under the curve (AUC) for discriminating HCC from liver cirrhosis (0.86), followed by IL6 (0.82), AFP (0.72), and platelet count (0.6)." (PMID 34714420, 2021). "In our study, high IL6 values were associated with high total bilirubin, low albumin, and high mALBI grade; and high IL8 values were associated with liver cirrhosis, alcoholic liver disease, and portal vein invasion." (PMID 34080071, 2021). "Given the described power of serum IL-6 levels to predict mortality of patients with liver cirrhosis, this parameter was chosen to further assess the level of systemic inflammation in our study." (PMID 32357568, 2020). "Many studies have reported high levels of the proinflammatory cytokine IL-6 in experimental models and patients with liver cirrhosis." (PMID 31233564, 2019). "In patients with liver cirrhosis, the serum selenium concentration was statistically lower, whereas serum IL-6 and GDF-15 concentrations were higher than those in the control group." (PMID 28430124, 2017). "Systemic levels of adiponectin, omentin, resistin, galectin-3 and IL-6 are higher in patients with liver cirrhosis, while chemerin is reduced." (PMID 28661458, 2017). "The previous studies revealed that increased levels of TNF-α as well as IL-2, IL-6, and IL-10 in serum of patients play important roles in the progress of inflammation of severe hepatitis B-related liver cirrhosis." (PMID 27975051, 2016). "There was significant positive correlation between HGF, IL6, IL-1α, and stage of liver cirrhosis (p < 0.001) (–8)." (PMID 26448742, 2015). "Increased systemic IL-6 in patients with liver cirrhosis can be explained by an impaired hepatic removal of IL-6." (PMID 26448742, 2015). "The concentrations of IL-6 in the group with classes A, B, and C liver cirrhosis were significantly higher than those in the control group." (PMID 26448742, 2015). "The univariate logistic regression analysis showed that levels of IL-1α, IL-6, and HGF had influenced liver cirrhosis risk (p < 0.001)." (PMID 26448742, 2015). "In patients with liver cirrhosis, however, acute phase response is impaired although systemic IL-6 is markedly increased." (PMID 26448742, 2015).
liver cirrhosis (continued). "Serum sCD14 and IL-6 were increased in HIV/HCV-coinfected patients with liver cirrhosis in comparison with those with chronic hepatitis or HIV-monoinfected individuals." (PMID 25775475, 2015). "A statistically significant positive correlation was found between concentrations of HGF versus concentrations of IL-1α and IL-6 in the group of patients with liver cirrhosis." (PMID 26448742, 2015). "The expression of IL-6 on hepatocytes, its upregulation by hepatitis B virus X protein, and its increased hepatic expression in liver cirrhosis have made IL-6 an intriguing cytokine to study in HCC." (PMID 23519638, 2013). "Patients with liver cirrhosis showed significant increase in serum IL-6 as compared with HCC patients and the control subjects." (PMID 22396913, 2012). "Accordingly, serum IL-6 concentration of liver cirrhosis patients is also higher than normal." (PMID 38762176, 2024). "It should be noted that patients with liver cirrhosis had a trend of higher serum IL-6 (p = 0.086)." (PMID 38791005, 2024). "Whether the pro‐IL‐6 effects of AA lead to amelioration or worsening of liver cirrhosis still needs further study." (PMID 39501714, 2024). "Finally, we assayed the hepatic IL-6 expression in human biopsies and found that IL-6 is significantly upregulated in the liver cirrhosis patients as indicated by Western blot and qRT-PCR." (PMID 38762176, 2024). "Liver cirrhosis was significantly associated with IL-6 and IL-8 over the median but not with the TNF-α values." (PMID 36009045, 2022). "The MDM2 mRNA levels of patients with HBV-related HCC were higher than those of patients with liver cirrhosis and chronic hepatitis B. The plasma levels of IL-6 and TNF-α were significantly higher in HBV-related HCC patients than that in liver cirrhosis and chronic hepatitis B patients." (PMID 33173438, 2020). "Thus, the increased IL-6 levels in patients with liver cirrhosis lead to the transformation of naive T cells into Th17 cells and a reduced number of Treg cells and elevated number of Th17 cells, resulting in Treg/Th17 imbalance." (PMID 31639000, 2019). "Additional experiments demonstrating the impact of IFNγ on TNFα and IL-6 production by CD14positive myeloid ascites suggested that NK cells might have indeed a regulatory role during peritonitis in patients with liver cirrhosis." (PMID 31440239, 2019). "Significant suppression of IL-6 mRNA levels by KCT-01 was increased in the liver of W4P variant hydrodynamic injection mice, strongly indicating its preventive role in the progression of liver cirrhosis or HCC." (PMID 30069220, 2018). "High IL-6 in patients with liver cirrhosis is partly due to impaired hepatic clearance." (PMID 28661458, 2017). "Basically, most of the studies show increased systemic IL-6 in patients with liver cirrhosis." (PMID 28661458, 2017). "Improvement of hepatic IL-6 removal and signaling may partly ameliorate liver function of patients with liver cirrhosis." (PMID 26448742, 2015). "Hence, fecal IL-6 levels may be suitable as an early biomarker of decompensation in patients with liver cirrhosis." (PMID 37189804, 2023). "Furthermore, GSH has been shown to inhibit IL-6 production in patients with liver cirrhosis." (PMID 31024337, 2019). "In more detail, levels of the pro-inflammatory mediators CRP, tPA, IL-6, IL-8, HGF, M-CSF, IL-2Ra, IP-10, and MIP-1a were significantly increased in patients with decompensated liver cirrhosis compared with healthy controls." (PMID 41028194, 2025). "In liver cirrhosis, Kupffer cells are activated and release multiple inflammatory mediators and chemokines, such as tumor necrosis factor (TNF-α), interleukin-6 (IL-6), and reactive oxygen species (ROS)." (PMID 39958826, 2025). "In all patients with liver cirrhosis, the quantity of bactDNA in ascites correlated strongly with ascites markers of inflammation such as PMN count, ascites WBC and ascites IL-6 levels." (PMID 38962151, 2024).
liver cirrhosis (continued). "Meanwhile, the expression of IL-6 positively correlates with α-SMA, the representative marker of HSC activation, in the biopsies of liver cirrhosis patients as well." (PMID 38762176, 2024). "A meta-analysis study found that IL-6 concentrations were considerably higher in the HCC group than in healthy participants and patients with liver cirrhosis." (PMID 39071840, 2024). "In another study, the inhibition of TNF-α, IL-1β, and IL-6 overexpression by CLX in spleen tissues, suppressed splenomegaly, contributed to the development of liver cirrhosis." (PMID 35884918, 2022). "In this study, elevation of serum Il-1α, IL6, and HGF levels correlated with the progression of liver cirrhosis." (PMID 26448742, 2015). "Other authors observed higher Il-6 and TNF-α concentrations in patients with liver cirrhosis compared with healthy volunteers." (PMID 26090463, 2015). "In this study, the altered intestinal epithelial barrier function in rats with liver cirrhosis was observed with an increase in TNF-α and IL-6 expression levels in small intestine." (PMID 25171482, 2014). "Similarly, the serum IL-6 concentration positively correlates with the expression of Fendrr, Col I and α-SMA in the specimens of liver cirrhosis patients." (PMID 38762176, 2024). "Moreover, we next measured the levels of the inflammatory cytokines, including IL-6, CXCL1, IL-1β, and TNF-α, in the intestine to examine the role of liver cirrhosis on inflammatory response following vitamin D treatment." (PMID 37273916, 2023). "The correlations with CRP (r = −0.160, p = 0.079) and procalcitonin (r = 0.153, p = 0.099) were not significant when patients with liver cirrhosis were excluded, whereas IL-6 still positively correlated with sCD137 (r = 0.202, p = 0.029)." (PMID 38139346, 2023). "However, pretreatment inhibited the depletion of IL-10 and elevation of TNF-α and IL-6 levels, which shows its anti-inflammatory effect on TAA-induced liver cirrhosis in the rat." (PMID 36458098, 2023). "Besides high IL6 and high IL8, liver cirrhosis (p = 0.032), Child–Pugh class B (p = 0.014), albumin < 36 g/L (p = 0.024), total bilirubin ≥ 17 μmol/L (p = 0.009), and higher (2b and 3) mALBI grade (p = 0.007) were associated with worse outcome." (PMID 34080071, 2021). "Though patients with liver cirrhosis and ascites have higher IL-6 and IL-8 in serum than those without ascites, serum leptin is unchanged." (PMID 28661458, 2017). "Similarly, for progression from liver cirrhosis to HCC model 3, the HBV viral load (p=0.03, OR = 2.45, and 95% CI: 1.69–3.65), IL-6 levels (p=0.04, OR = 3.45, and 95% CI: 2.01–6.9), and TRL2 rs3804099 polymorphism (p=0.01, OR = 4.25, and 95% CI: 2.14–13.5) are the independent risk factors." (PMID 39071840, 2024). "Thus, both HCV-related liver cirrhosis and HIV-induced intestinal barrier lesion could be operative and justify the increased values of sCD14 and IL-6 in HIV/HCV cirrhotic patients." (PMID 25775475, 2015). "In patients with liver cirrhosis, plasma LBP was also positively correlated with procalcitonin (r = 0.480, p = 0.004) and CRP (r = 0.703, p < 0.001) but not with IL-6 and immune cell numbers." (PMID 39997462, 2025). "Comparison of liver cirrhosis patients with and without HCC (n = 55) revealed significantly high AFP (p < 0.001) and IL-6 (p < 0.001) levels." (PMID 29963457, 2018). "Comparison of HCC patients with liver cirrhosis cases with no diagnosis of HCC (n = 55) revealed significantly high AFP (p < 0.001) and IL-6 levels (p < 0.001) in the HCC group." (PMID 29963457, 2018). "Comparison of HCC patients with liver cirrhosis cases with no diagnosis of HCC revealed significantly high AFP (p < 0.001) and IL-6 levels (p < 0.001) in HCC group." (PMID 29963457, 2018).
liver cirrhosis (continued). "Excitingly, IL-1R, IL-6, or IL-17A, but not IL12 deletion in dKO mice respectively partly prolonged the survival time of dKO mice which means that production of pro-inflammation cytokines is responsible for the nosogenesis, at least partly, of liver cirrhosis." (PMID 35354799, 2022). "Based on this reasoning, the aim of the present study is to analyze the relationship of Klotho with proinflammatory cytokines (TNF-α, IL-6, and IL-8) and the lipid peroxidation products (Malondialdhyde = MDA) among alcoholics with or without liver cirrhosis, and its relationship with survival." (PMID 36009045, 2022). "Thirty control cases, 55 liver cirrhosis patients without HCC, and 75 liver cirrhosis cases with HCC were evaluated in the current trial; AFP (p < 0.001) and IL-6 (p < 0.001) were found to be significantly higher among HCC cases, as compared with control group." (PMID 29963457, 2018).